TNF (tumor necrosis factor)
Diseases named in the same sentence as TNF in open-access papers (continued):
Sharing a sentence is not in itself a finding about the gene and the disease.
chronic hepatitis (31 papers, 2005 to 2025). An active inflammatory process affecting the liver for more than six months. "HCC develops in the course of chronic hepatitis, which is associated with the continuous production of pro-inflammatory cytokines (TNF-α), which cause excessive activation of the STAT3 pathway, which promotes cancer development (positive feedback loop)." (PMID 39409068, 2024). "Differentialy expressed TNF-α from HBV-specific CD8 + T cells was associated with the outcomes of chronic HBV infection including asymptomatic status, active chronic hepatitis and HBV-related HCC45." (PMID 33219288, 2020). "Among these factors, we were particularly interested on TNFα, since most HCC patients in our study had chronic hepatitis history and TNFα is a well-known pro-inflammatory cytokine." (PMID 32641749, 2020). "FasL expression on CD11b+ Kupffer cells/Mφs was significantly blunted by anti TNF antibody treatment, which strongly suggests that these cells and FasL are the final effector of this chronic hepatitis model." (PMID 27708340, 2016). "As IL-6 and TNF-α are major inflammatory factors in chronic hepatitis, these results suggest that chronic inflammation may contribute to miR-122 downregulation in CHB." (PMID 26933995, 2016). "In addition, we measured plasma TNFα, a marker of chronic hepatitis and inflammation." (PMID 30322375, 2018). "Furthermore, to investigate whether TNF-α and IL-6 played particularly critical roles in the pathogenesis of chronic hepatitis in the transgenic mice, we neutralized TNF-α and blocked the IL-6 receptor in the livers of these mice." (PMID 23284733, 2012). "We used HSECs treated with IFN-γ and TNF-α in flow-based adhesion assays to model inflamed HSEC, which express ICAM-1, VCAM-1, and CXCR3 ligands in chronic hepatitis." (PMID 22796894, 2012). "We also demonstrated that the onset of chronic hepatitis in CN2-29(+/−)/MxCre(+/−) mice was mainly attributable to inflammatory cytokines, (tumor necrosis factor) TNF-α and (interleukin) IL-6." (PMID 23284733, 2012). "Indeed, CAHL in normal liver cells was upregulated in the presence of a proinflammatory cytokine, tumor necrosis factor (TNF)-α with dose dependent manner, suggesting that CAHL can express to some extent in the liver under chronic hepatitis." (PMID 21559518, 2011). "In the APAP-induced acute hepatitis model and RFP-induced chronic hepatitis model, cPBA-BE could resist GSH depletion, reduce oxidative stress, block the infiltration of neutrophils, and lower the secretion of inflammatory cytokines TNF-α and IL-1β more effectively than free BE." (PMID 34373743, 2021).
kidney injury (31 papers, 2015 to 2025). Trauma to the kidney. "Melittin exerts antioxidant-anti-inflammatory renoprotection by suppressing NF-κB/TNF-α signaling and engaging Nrf2/HO-1, as shown in recent kidney injury models (including aminoglycoside AKI)." (PMID 41301702, 2025). "In contrast, microvascular CD11c+F480− dendritic cells hardly secrete TNF in homeostatic conditions but significantly increase their capacity to secrete TNF after kidney injury." (PMID 40346040, 2025). "Since S100A8/A9 can activate different receptors, such as TLR4, to promote leukocyte recruitment and secretion of proinflammatory cytokines, such as IL-6 and TNF-α, leading to kidney injury." (PMID 37547329, 2023). "Endothelial inflammation is one of the drivers of postoperative organ damage, including acute kidney injury Tumour Necrosis Factor alpha (TNF-α) is an important component of surgery-induced pro-inflammatory activation of endothelial cells." (PMID 36532777, 2022). "Our previous study also showed Dex protects septic acute kidney injury through reduced cytokines TNF-α and MCP-1 production." (PMID 29351316, 2018). "Semaglutide could act as a protective agent against acute kidney injury by reducing inflammatory molecules such as tumor necrosis factor-alpha (TNF-α) and its cognate receptor, TNF-α R, interleukine-6 (IL-6)." (PMID 36937464, 2023). "The underlying mechanism study showed that NF-κB activation triggers the release of inflammatory cytokines such as interleukin-1beta (IL-1β), interleukin-6 (IL-6) and tumor necrosis factor alpha (TNF-α) that exacerbating kidney injury (Place and Kanneganti., 2018)." (PMID 36278223, 2022). "In particular, TNF-α, IL-1β, and IL-6 play a key role in cisplatin-induced kidney injury." (PMID 32089779, 2020). "In addition, Dex protects septic acute kidney injury through reducing TNF-α and MCP-1 expression and inhibiting HDAC." (PMID 29351316, 2018). "TNF-α is the main cytokine involved in acute kidney injury induced by cisplatin." (PMID 28303105, 2017). "Propofol has been demonstrated to inhibit TNF-α, IL-6, and CXCL-10 expression in I/R-induced kidney injury." (PMID 39054453, 2024). "The protein expression of the kidney injury molecule KIM-1 and the inflammatory factors TNF-α and MCP-1 revealed that inhibition of necroptosis decreased HR-induced kidney injury, whereas inhibition of necroptosis inhibited the inflammation caused by AKI." (PMID 35164651, 2022). "Authors showed significantly attenuated expression of NF-κB messenger RNA, inhibiting overactivation of NF-κB and further reducing the generation of tumor necrosis factor (TNF)-α and ICAM-1 by MSCs in an inflammatory mouse model of kidney injury." (PMID 32843073, 2020). "Our data show that five inflammation markers (TNF-α, TNFR1, TNFR2, ICAM-1, and adiponectin) also correlated with the extent of kidney injury in African American men, as determined by the UACR." (PMID 30868076, 2019). "Moreover, an increase in inflammatory (TNF-α and TGF-β) and apoptotic (caspace-3) markers, an elevation in gene-based kidney injuries markers (Kim-1 and lipocalin-2), and pathological tissue changes were determined." (PMID 39837868, 2025). "In response to noxious stimuli, the innate immune system reacts by engaging and activating adaptive immune cells, and activated T-lymphocytes can secrete TNF -α, IL-17α, and interferon-gamma (IFN-γ), all of which also contribute to elevated blood pressure and kidney injury." (PMID 39311633, 2024). "Similarly, FN exhibited dose-dependent anti-inflammatory action via suppressing the pro-inflammatory mediators, involving IL-1β and TNF-α, as part of its renal protective mechanism against MTX-induced kidney injury." (PMID 35712704, 2022). "In summary, TNF-α and KIM-1 were significantly elevated following DR-induced kidney injury." (PMID 32575412, 2020).
kidney injury (continued). "Indeed, urinary ICAM-1, plasma TNF-α, and adiponectin had moderate positive correlations with UACR while plasma TNFR1 and TNFR2 levels were strongly correlated with kidney injury, indicated by multiple biomarkers of kidney injury." (PMID 30868076, 2019).
sacroiliitis (31 papers, 2009 to 2025). "Infliximab, a monoclonal antibody targeting TNF-alpha, was first reported in a case study in 2009 for HLA B27-negative patients with sacroiliitis, showing promising results after a 2-year follow-up." (PMID 40004824, 2025). "In assessing anti-TNF failure specifically for sacroiliitis, sacroiliac joint imaging is considered the paramount factor influencing clinical decision-making by 65% of rheumatologists." (PMID 40364197, 2025). "While anti-TNF is recommended for sacroiliitis, resource limitations, particularly limited access and high cost of biologic drugs, lead to alternative combinations of DMARDs and NSAIDs in some countries, including Thailand." (PMID 39215234, 2024). "In a patient with persistent sacroiliitis with beginning destruction and otherwise low clinical disease activity, 60% would start a TNF-α inhibitor and 21% canakinumab (case 19)." (PMID 37752496, 2023). "Patients with sacroiliitis showed significantly decreased SPARCC scores after 3 months of TNF-α inhibitor treatment, indicating TNF-α inhibitor therapy is effective in treating axSpA patients." (PMID 35804360, 2022). "Nonsteroidal anti-inflammatory drugs and disease-modifying antirheumatic drugs were the most commonly prescribed treatments, with anti-TNF agents primarily being initiation for sacroiliitis." (PMID 28464909, 2017). "Specifically, the efficacy of anti-TNFα and DMARDs as treatments for sacroiliitis was assessed with both drugs alone or in combination." (PMID 26832154, 2016). "The role of IL-6 was not considered crucial in an animal model of tumour necrosis factor- (TNF-) mediated bilateral sacroiliitis." (PMID 26339141, 2015). "Apart from a previous report from our group, finding inflammatory sacroiliitis lesions on MRI to predict better drug survival of a first TNF inhibitor in nr-axSpA, data on anti-TNF adherence in this diagnosis remain sparse." (PMID 26703005, 2015). "Furthermore, hip arthritis and sacroiliitis often prove resistant to TNF inhibitor therapy, highlighting a potential limitation in the ability of these agents to prevent disease progression in these specific locations." (PMID 40364197, 2025). "High levels of TNF were found in sacroiliitis during the early stages of AS." (PMID 39031474, 2024). "Only 12% of patients who were treating by Anti-TNF medications had grade 2 or higher sacroiliitis." (PMID 34863148, 2021). "Compared to SIJ controls, the subchondral microvessel density, number of CD68+ multinuclear osteoclasts, and the levels of VEGF, caspase-3, MMP-3, and TNF-α expressed at the interface of the bone and cartilage were significantly higher in patients with sacroiliitis." (PMID 29884210, 2018). "Abundant TNF-α-producing cells have been described in early sacroiliitis lesions from AS patients." (PMID 28791018, 2017). "Interestingly, DKK-1 inhibition also leads to a bilateral erosive change and ankylosis of the sacroiliac joints in TNF TG mice, which have symptoms that mimic those of sacroiliitis in humans." (PMID 26634249, 2015). "MRI abnormalities in bone marrow edema (BME) were compared before and after treatment in order to compare the efficacy of anti-TNF-α and DMARD, alone or in combination, as treatments for sacroiliitis." (PMID 26832154, 2016). "Anti-tumor necrosis factor (TNF) agents can also be administered systemically to address SIJ pain, but their use is recommended only under specific conditions, such as persistent high disease activity, elevated CRP levels, or positive imaging for sacroiliitis." (PMID 40004824, 2025). "Moreover, of the 23 patients affected by sacroiliitis in ERA, 13 patients were in treatment with DMARDs (12 with sulphasalazine and 1 with Methotrexate), while 10 patients were in treatment with anti-TNF alpha inhibitors." (PMID 34055840, 2021). "In an animal model of TNF-mediated bilateral sacroiliitis, however, IL-6 was not a crucial regulator of the disease process." (PMID 22404969, 2012).
sacroiliitis (continued). "The presence or absence of sacoiliitis could explain the findings in ERA patients in the larger cohort because sacroiliitis is most commonly seen in ERA, MTX is not recommended for sacroiliitis, and anti-TNF therapy is warranted if non-steroidal anti-inflammatories do not control sacroiliitis." (PMID 34419107, 2021). "Two mouse models over-expressing TNF-α, either through a transgenic approach (hTNFtg), or through increasing TNF mRNA stability by deleting the 3' ARE regulatory elements (TNFΔARE), show systemic inflammation, gut disease and sacroiliitis but do not spontaneously develop ankylosis." (PMID 23171658, 2012).
arteriosclerosis (30 papers, 2008 to 2025). A vascular disorder characterized by thickening and hardening of the walls of the arteries. "As one of the inflammatory cytokines, tumor necrosis factor-alpha (TNF-α) is an important risk factor in the process of arteriosclerosis." (PMID 38650631, 2024). "Meanwhile, bioactive substances secreted by adipose tissue, such as angiotensinogen, IL-6 and TNF-α, are associated with changes in vascular inflammation and arteriosclerosis, leading to increased blood pressure." (PMID 35937205, 2022). "One effect of adiponectin is the reduction of TNF-alpha production in macrophages, counteracting its pro-inflammatory effects on the arterial wall and possibly protecting against arteriosclerosis, and it correlates negatively with BMI." (PMID 35053667, 2022). "HASMC cells are known to produce inflammatory cytokines involving IL-6, IL-1β, and TNF-α during arteriosclerosis activity." (PMID 33841150, 2021). "Plasma APN, PAI-1, IL-6 and TNF-α levels can be used as monitoring indicators of intracranial and extracranial arteriosclerosis." (PMID 32548044, 2020). "TNFα is a representative inflammatory cytokine that participates in the development of arteriosclerosis." (PMID 30643517, 2018). "Raloxifene also decreases inflammatory cytokines such as TNF-α, IL-6, and MCP-1 that cause arteriosclerosis." (PMID 26345606, 2015). "TNF-α is a well-known potent pro-inflammatory cytokine involved in the pathogenesis of arteriosclerosis, and plays a pivotal role in orchestrating the cytokine cascade in many inflammatory diseases because of this role as a “master-regulator” of inflammatory cytokine production." (PMID 29025416, 2017). "The level of plasma APN in the intracranial and extracranial arteriosclerosis group was significantly lower than that in the control group, and the plasma levels of PAI-1, TNF-α and IL-6 were significantly higher than those in the control group." (PMID 32548044, 2020). "Human aortic vascular smooth muscle cells (HASMCs), in which Moenckeberg’s arteriosclerosis is induced in CKD patients, demonstrated calcification induced by iron and pro-inflammatory cytokine stimulation (TNF-alpha)." (PMID 29330517, 2018). "In previous studies, PC was found to reduce the mRNA expressions of TNF-α and IL-6 and to combat chronic nonbacterial prostatitis (a male disease) and arteriosclerosis." (PMID 34832910, 2021). "The observed significant inhibition of TNF-α and chemokine (IL-8 and MCP-1) production is of special interest for treating inflammatory diseases such as rheumatic arthritis, respiratory diseases, and arteriosclerosis." (PMID 29695965, 2018). "In addition to pro-inflammatory cytokines such as TNF-α, IL-1β, IL-6, and MCP-1, chemokines such as macrophage migration inhibitory factor and CXCL12 play an important role in the initiation and the progression of arteriosclerosis." (PMID 36670934, 2022).
astrocytoma (30 papers, 1994 to 2025). "In summary, our study demonstrates that dysregulation of the TNF-α signaling axis—including upregulation of TNF-α, IL-1β, and MAP3K8—is a hallmark of high-grade astrocytomas and correlates with worse patient outcomes." (PMID 40565357, 2025). "IFN-β, TNF-α, and IL-1β induce the generation of Aβ in primary human astrocytes and astrocytoma cells." (PMID 34685770, 2021). "LPS stimulates astrocytes to secrete cytokines including IL-6 and TNF-α, activates astrocytoma cells to secrete IL-6 and IL-8 and monocytes to secrete IL-8 under the influence of Aβ peptides." (PMID 34685770, 2021). "Reports indicate that the secretion and expression of tumor necrosis factor (TNF)-α, inflammatory cytokines, and interleukin (IL)-6 are inhibited in human astrocytoma cells treated with soluble chitosan." (PMID 34663339, 2021). "Results and Conclusions: ET-1 secretion by astrocytoma cells was only stimulated by the pro-inflammatory cytokines IL-1β and TNF-α." (PMID 31969819, 2019). "We found that ET-1 secretion in human astrocytoma cells was stimulated by the pro-inflammatory cytokines IL-1β and TNF-α, which are known to be present in focal MS lesions." (PMID 31969819, 2019). "Remarkably, some stimuli, such as IL-1 or TNF, up-regulate IL-8 by more than 100-fold in human astrocytoma and alveolar epithelial cell lines, suggesting a synergistic effect of EAEC by inducing high TNF-α and IL-8 secretion." (PMID 27774437, 2016). "Tumor necrosis factor (TNF)-related apoptosis-inducing ligand (TRAIL) induced MMP9 expression in human astrocytoma cells through activation of extracellular signal-regulated protein kinase (ERK)." (PMID 27022952, 2016). "We compared protein levels with Western blotting analysis, and we investigated CK2 activity in human U373 astrocytoma cells and human primary adult astrocytes stimulated with IL-1β or TNF-α." (PMID 26732432, 2016). "It was shown that both PRP and NP at a dose of 10 μg/ml, as well as TNFα (50 pg/ml) used as a reference sample stimulate human astrocytoma cell line U87 to release significant amounts of NGF." (PMID 25841889, 2015). "Previous publications demonstrated that activation of β2-adrenergic receptors enhances TNF-α-induced expression of IL-6 in both rat astrocytes and the human 1321 N1 astrocytoma cell line." (PMID 24479486, 2014). "Genes that are susceptible to astrocytic crosstalk between β2-adrenergic receptors (stimulated by clenbuterol) and TNF-α were identified by qPCR-macroarray-based gene expression analysis in a human 1321 N1 astrocytoma cell line." (PMID 24479486, 2014). "In both groups, GSVA showed that astrocytoma was associated with hallmark gene sets, such as KRAS signaling, fatty acid metabolism, and hypoxia, and oligodendroglioma was associated with the EMT, DDR, TGF-β, and TNF-α pathways." (PMID 35287567, 2022). "So far, pro-inflammatory factors such as LPS or IL-1β and TNFα were reported to upregulate PTPRG in astrocytoma cell line or astrocyte culture and also appear to associate to specific myeloid lineages, such as the differentiation of monocytes to dendritic cells." (PMID 35071225, 2021). "However, we recently showed that the pro-inflammatory cytokines IL-1β and TNF-α, which are present in active inflammatory MS plaques, stimulated ET-1 secretion in cultured human astrocytoma cells." (PMID 32765401, 2020). "Moreover, the NMDA receptor antagonist memantine displays protective effects against streptozotocin treatment-induced activation of rat astrocytoma cell line by reducing TNF-α protein levels." (PMID 30355282, 2018). "Furthermore, human astrocytoma cells were challenged with 0, 1, 10, 100, or 500 ng/ml of IL-17 for 24 h, and then the production of pro-inflammatory cytokines IL-1β, IL-6 and TNF-α were determined by ELISA." (PMID 28281545, 2017).